TAAR8 (trace amine associated receptor 8)
Description:
Olfactory receptor specific for trace amines (By similarity). Trace amine compounds are enriched in animal body fluids and act on trace amine-associated receptors (TAARs) to elicit both intraspecific and interspecific innate behaviors (By similarity). Ligand-binding causes a conformation change that triggers signaling via G alpha proteins, possibly G(i)/G(o) G alpha proteins.
Synonyms: TaR-8; TaR-5; GPR102; TA5; TAR5; TRAR5
Tractability: Small molecule: it belongs to a druggable protein family. Antibody: UniProt places it where antibodies can reach, with high confidence; its Gene Ontology location is reachable by antibodies, with high confidence; UniProt predicts a signal peptide or a membrane-spanning region.
Target class: Monoamine receptor; Trace amine receptor; Membrane receptor; Family A G protein-coupled receptor; Small molecule receptor (family A GPCR)
Gene: Protein-coding gene on chromosome 6 (132,552,672 to 132,553,756, forward strand). Ensembl gene ENSG00000146385.
Subcellular location: Cell membrane
Pathways (Reactome):
Signal Transduction: Amine ligand-binding receptors; G alpha (s) signalling events
Gene Ontology:
Molecular function: protein binding; G protein-coupled receptor activity; trace-amine receptor activity
Biological process: G protein-coupled receptor signaling pathway
Cellular component: plasma membrane; membrane
Genetic constraint (gnomAD): Missense variants: 452 observed, 423.23 expected, observed/expected ratio (o/e) 1.07, 90% interval 0.99 to 1.15. Synonymous variants: 155 observed, 158.14 expected, observed/expected ratio (o/e) 0.98, 90% interval 0.86 to 1.12.
Homologues: Orthologues: mouse Taar8b (81% identical), rat Taar8a (80% identical), mouse Taar8c (80% identical), mouse Taar8a (79% identical), rat Taar8c (78% identical). Paralogues in human: TAAR6 (80% identical), TAAR9 (68% identical), TAAR5 (43% identical), TAAR1 (39% identical), TAAR2 (34% identical), CHRM5 (28% identical), HTR1A (27% identical), HTR1D (27% identical), HRH2 (27% identical), HTR4 (27% identical), CHRM2 (26% identical), DRD1 (26% identical), and 13 more.
Diseases named in the same sentence as TAAR8 in open-access papers:
TAAR8 is named in the same sentence as 5 diseases in open-access papers, as found by Europe PMC text mining. Sharing a sentence is not in itself a finding about the gene and the disease. The quoted sentences say what the papers report.
breast carcinoma (1 paper, 2019). "Decreases in TAAR8 expression was different between the histological subtypes of breast cancer." (PMID 30718646, 2019). "Indeed, higher expression of TAAR1, TAAR2, TAAR4, TAAR5, TAAR8 (in ER- cases) and TAAR9 provided better survival in breast cancer." (PMID 30718646, 2019).
melanoma (1 paper, 2022). A malignant, usually aggressive tumor composed of atypical, neoplastic melanocytes. "Differential expression analysis demonstrated the drastic decrease of TAAR1, TAAR2, TAAR5, TAAR6, and TAAR8 expression in melanomas compared to benign nevi with only TAAR6, TAAR8, and TAAR9 remaining detectable in malignant tumors." (PMID 35053262, 2022). "TAAR8, TAAR9, DRD1, DRD2, and DRD5 expression was also slightly upregulated in melanomas after immunotherapy (Padj < 0.05)." (PMID 35053262, 2022). "In contrast, TAAR6, TAAR8, and TAAR9 were expressed in 12.7%, 11.3%, and 5.3% of tumor specimens, respectively, so their expression is comparable with DRD2, of which expression and activity are well established in melanoma." (PMID 35053262, 2022). "In this study, TAAR6, TAAR8, and TAAR9 expression was found in melanoma samples." (PMID 35053262, 2022). "However, TAAR6, TAAR8, and TAAR9 were still expressed in melanoma." (PMID 35053262, 2022).
cancer (3 papers, 2018 to 2023). A tumor composed of atypical neoplastic, often pleomorphic cells that invade other tissues. "We estimated TAARs’ (including TAAR1, TAAR2, TAAR5, TAAR6, TAAR8, and TAAR9) associations with BC stage, grade, and molecular subtypes in these data and identified that the expression of all TAARs was associated with more unfavorable cancer subtypes, including basal-like and HER2-positive tumors." (PMID 37759760, 2023). "RNAseq data from 12 published cancer studies obtained from cBioPortal detected RNA for TAAR1, TAAR2, TAAR5, TAAR6, TAAR8, and TAAR9 in various cancers." (PMID 29997511, 2018).
tumor (2 papers, 2022 to 2023). "The overlap between genes co-expressed with TAARs in primary tumors and metastatic lesions is significant, and we found correlations between the expression levels of TAAR1, TAAR2, TAAR5, TAAR8, and TAAR9 and genes associated with neuroactive ligand signaling in both kinds of neoplasms." (PMID 37759760, 2023). "The identified differences in TAAR2 and TAAR5 expression levels between tumor cells and stroma seem to be reproducible in different groups, including inflammatory cancer, whilst tumorous and stromal cells demonstrate similar expression levels of TAAR1, TAAR6, and TAAR8." (PMID 37759760, 2023).
TAAR8 also shares sentences with these, for which no sentence is quoted: invasive breast carcinoma (1 paper).